USP7 (ubiquitin specific peptidase 7)
Diseases named in the same sentence as USP7 in open-access papers (continued):
Sharing a sentence is not in itself a finding about the gene and the disease.
cancer (continued). "USP7 is emerging as a promising pharmacological target for interference with the UPS in several human cancers." (PMID 36186590, 2022). "Considerable progress has been made over the past several years in understanding the role of USP7 in modulating the immune response in cancer patients." (PMID 36428632, 2022). "Collectively, the results from these studies support the pursuit of USP7 as a promising and attractive drug target for cancer therapeutics." (PMID 36186590, 2022). "The development of specific USP7 inhibitors offers interesting new avenues of druggability of DUBs for cancer, neurodegenerative and other diseases." (PMID 35585066, 2022). "GSEA of these DEGs revealed that HNSCC samples with USP7 overexpression harbored genes significantly enriched with cancer-related gene signatures such as Myc-targets, EMT and two previously reported Hippo-YAP/TAZ cancer signatures." (PMID 35931679, 2022). "USP7 expression is frequently misregulated in various cancer types and has context-dependent tumor suppressor or oncogenic roles." (PMID 36342772, 2022). "In this review, we will provide a summary overview of the recent advances in the development of USP7 inhibitors for cancer treatment." (PMID 36186590, 2022). "To substantiate the translational potentials of USP7-TAZ axis as novel therapeutic targets, we exploited a HNSCC PDX and P5091 which had been verified as a potent inhibitor of USP7 in preclinical cancer models." (PMID 35931679, 2022). "In this review, we briefly covered the status of USP7-targeted drug development with the focus on cancer immunotherapy and combination with other therapeutic approaches." (PMID 36428632, 2022). "USP7 inhibition leads to the modulation of multiple immune-oncology targets, offering a promising opportunity to improve the efficacy of cancer immunotherapy." (PMID 36428632, 2022). "The synergistic effect of combining USP7 inhibition with cancer immunotherapy is a promising therapeutic approach, though its clinical efficacy is yet to be proven." (PMID 36428632, 2022). "Several small molecule inhibitors of USP7 have been developed for cancer treatment, of which P5091 and P22077 were most widely studied." (PMID 35307036, 2022). "Previous research reported that the USP7 protein stability is modulated with the ubiquitin proteasome pathway in the cancer cells." (PMID 36152057, 2022). "The combination of cytarabine with the USP7 inhibitor P22077 has a synergistic impact on promoting anti-leukemic activity and can help overcome chemoresistance in cancer cells." (PMID 36428632, 2022). "Among these, USPs are the largest DUB family with ∼60 proteases in humans and USP7 is one of the most intensively studied due to its pivotal role in cancer progression." (PMID 36186590, 2022). "A number of scientific reports have proposed that USP7 is a key effector protein in the emergence of resistance to doxorubicin and paclitaxel chemotherapies in various cancers." (PMID 36291159, 2022). "The abnormal expression of USP7 is found in various malignant tumors and a high expression signature generally indicates poor tumor prognosis." (PMID 36186590, 2022). "We review the potential benefits of the application of USP7 inhibitors for cancer immunotherapy and their interplay with other cancer therapeutics." (PMID 36428632, 2022). "Although the pro-tumorigenic roles of USP7 have been reported among multiple human cancers, the expression of USP7 and its biological roles in HSNCC remained underexplored." (PMID 35931679, 2022).
cancer (continued). "Noticeably, several chemical compounds have been identified to selectively target USP7 with remarkable anti-cancer effects in preclinical cancer models." (PMID 35931679, 2022). "Recent studies confirm that USP7 and its inhibitors regulate cell proliferation and apoptosis, especially in cancers." (PMID 35432716, 2022). "Additional, small molecule inhibitors of USP7 were considered as potential therapies to delay cancer progression by many researchers." (PMID 35432716, 2022). "The results of a study conducted in chemosensitive patient-derived xenograft (PDX) models of SCLC revealed that inactivation of N-MYC restores cancer cell chemosensitivity through downregulation of ubiquitin-specific protease 7 (USP7) expression." (PMID 35508982, 2022). "This is further reinforced by the involvement of USP7 in the modulation of the immune response, considering the growing role of immunotherapy in cancer treatment." (PMID 36428632, 2022). "There is a burgeoning interest in inhibiting USP7 using small molecules as a potential new cancer therapy." (PMID 33664368, 2021). "USP7 is a ubiquitin-specific protease that displays a wide range of activities, making it an attractive candidate target for cancer treatment." (PMID 34113809, 2021). "The current study demonstrated that the expression of USP7 was relatively low in normal oral mucosa tissues adjacent to cancer tissues, but showed a high expression level in OSCC tissues, especially in poorly differentiated carcinomas." (PMID 34812471, 2021). "USP7 exhibits a high expression signature in various malignant tumors, and increased USP7 expression often indicates the poor tumor prognosis, suggesting that USP7 is a marker of tumor prognosis and a potential drug target for anti-tumor therapy." (PMID 33967786, 2021). "Increasing numbers of studies have reported that high USP7 expression participates in the progression of multiple cancers, including NSCLC." (PMID 34753486, 2021). "Recent studies have demonstrated that Ubiquitin-specific protease 7 (USP7) was upregulated in several types of cancers." (PMID 34812471, 2021). "USP7 is now considered to be an oncoprotein in many cancers due to the regulating the stability of other oncogenic proteins and inhibiting the nuclear translocation effects of oncogenic proteins." (PMID 34556124, 2021). "All these studies demonstrated that the role of USP7 is tumor suppressive or oncogenic, depending on the context of the cancers and its substrates." (PMID 33869052, 2021). "As a result, this kind of cross effect adds difficulty in determining the contribution of USP7 inhibition to the effect of the tested compound in cancer progression." (PMID 34869041, 2021). "In a wide variety of cancers, USP7 acts as an oncogene a good therapeutic target for cancer, and the high expression of USP7 leads to the progression of cancer." (PMID 34469054, 2021).
cancer (continued). "Ubiquitin-specific protease 7 (USP7) is a member of the deubiquitinase (DUBs) family and has an important implication in cancer development by altering the DNA damage response, apoptosis and cell cycle control." (PMID 33361335, 2021). "Our findings caution against a universal oncogene designation for USP7 while emphasizing the dosage-dependent consequences of USP7 inhibitors currently under development as potential cancer therapeutics." (PMID 33664368, 2021). "USP7 is a promising anticancer therapeutic target because of its aberrant expression and the oncogenic role in various cancers." (PMID 34469054, 2021). "One of the well-documented cancer-associated DUBs is HAUSP (herpes virus-associated ubiquitin-specific protease), also known as Ubiquitin Specific Protease 7 (USP7), an enzyme that is overexpressed in many solid and blood malignancies." (PMID 35052383, 2021). "This review summarizes the physiological and pathological functions of USP7 in immune signaling, DNA damage response, and cancers, as well as the regulatory mechanisms of its expression and activity." (PMID 34869041, 2021). "We also checked the effects of USP7 and hnRNPA1 on biological behavior of cancer cells, both USP7 and hnRNPA1 showed a positive link with increased cell viability, but had only slight influence on cell cycle." (PMID 34845198, 2021). "We demonstrated that the USP7/PRC2 complex drives cancer cell proliferation and tumorigenesis in vitro and in vivo." (PMID 33849069, 2021). "In this sense, we have shown that CDK1 is essential for the toxic effects of USP7 inhibitors in cancer cells." (PMID 34445496, 2021). "Of interest, it has also been suggested that inhibition of USP7 inhibits the migration and invasion of cancer cells." (PMID 34556124, 2021). "The therapeutic applications of pharmacological inhibitors of USP7 in cancer have been further examined." (PMID 33919439, 2021). "Our findings support a model by which upregulation of USP7 in cancers resulted in an elevated abundance of EZH2, as well as H2BK120ub1 removal and an increased level of H3K27me3, which is independent on the PRC1 complex." (PMID 33849069, 2021). "Inhibition of USP7 also induces endoplasmic reticulum (ER) stress due to the accumulation of polyubiquitinated protein substrates in cancer cells, which leads to increased intracellular reactive oxygen species (ROS)." (PMID 33869052, 2021). "USP7 is another promising target for the treatment of various cancers as it regulates the stability of a multitude of oncoproteins and tumor suppressors." (PMID 33324551, 2020). "For example, ADC-01, ADC-03, HBX41108, HBX19818, P5091, and P22077, which target USP7, are under preclinical investigation as candidates for anti-cancer drugs." (PMID 32781716, 2020). "While human trials of USP7 inhibitors have yet to be conducted, many of these compounds have been found to inhibit cancer cell growth in vitro, as well as in animal xenograft models." (PMID 32850836, 2020). "Our analysis revealed that the expression patterns of AURKB, CCNB1, PLK1, and USP7 were all higher in tumor tissues than in normal tissues, although their basal levels were different in each cancer." (PMID 33207738, 2020). "For instance, USP7 mRNA expression levels were found to correlate with genomic instability across the NCI-60 panel of cancer cell lines." (PMID 32850836, 2020).
cancer (continued). "Using XL177A, paired with XL177B, we focused our investigations on USP7 substrates or cellular features that predict growth suppressive effects in cancer in response to pharmacological inhibition of USP7." (PMID 32210275, 2020). "Ubiquitin-specific protease 7 (USP7) is a de-ubiquitin enzyme that plays an essential role in multiple cancers and becomes a target for treatment." (PMID 32002017, 2020). "USP7 knockdown effectively induced cell death in several cancer cells of lung, prostate, and cervix." (PMID 33207738, 2020). "The combination of potency, proteome-wide selectivity, and evidence of on-target mechanism across large panels of cancer cell lines nominate XL177A as a best-in-class cellular probe of USP7." (PMID 32210275, 2020). "Our results demonstrate that inhibiting USP7 is effective in treating cancer cell lines in vitro, even those that have resistance to mitotic catastrophe." (PMID 33207738, 2020). "In summary, here we report that the expression of USP7 is increased in mitosis and targeting USP7 using either a specific inhibitor or shRNA is effective in arresting cellular growth and inducing apoptosis via mitotic aberration in several cancer cell lines." (PMID 33207738, 2020). "Taken together, our results indicate critical role of USP7 in cancer development and chemoresistance." (PMID 32002017, 2020). "Originally identified as a potential anti-cancer target in a genome-wide RNA interference (RNAi) screen of catalytically active USPs, USP7 has recently attracted attention as a potential therapeutic target." (PMID 32354135, 2020). "In recent years, the USP family has emerged as an important target for anti-cancer drugs, and numerous studies of USP7 inhibitors are ongoing." (PMID 32370049, 2020). "USP7 has been proposed as a therapeutic target in several cancers because it has many reported substrates with a role in cancer progression, including FOXO4, MDM2, N-Myc, and PTEN." (PMID 32210275, 2020). "Recently, USP7 has become an attractive pharmacological target for inducing apoptotic cell death in cancer cells." (PMID 32850836, 2020). "In this work, we review the increasingly evident role of USP7 in maintaining genome stability, the links between USP7 deregulation and cancer progression, as well as the rationale of targeting USP7 in cancer therapy." (PMID 32850836, 2020). "Third, because targeting USP7 effectively results in mitotic catastrophe in cancer cells, a USP7 inhibitor can exert anticancer activity by inducing apoptosis in carcinomas with resistance to mitotic catastrophe." (PMID 33207738, 2020). "Research on numerous USP7 inhibitors is ongoing, and some inhibitors are undergoing clinical testing as anti-cancer drug candidates." (PMID 32370049, 2020). "Here, we demonstrated the effectiveness of targeting USP7 in advanced malignant cells showing high levels of USP7, especially in taxane-resistant cancer." (PMID 33207738, 2020).
cancer (continued). "Targeting of USP7 by the inhibitor P5091 induces cellular apoptosis of cancer cells in MM and counteracts bortezomib resistance." (PMID 33327527, 2020). "Although these molecules show good potency and selectivity against USP7, further in vivo studies will be required to evaluate their therapeutic relevance in cancer treatment." (PMID 32531973, 2020). "By inducing PLK1 degradation, USP7 inhibition with P5091 was, however, found to sensitize taxane-resistant cancer cells to paclitaxel and docetaxel and to trigger apoptotic cell death." (PMID 32850836, 2020). "We thus sought to use XL177A/B to gain a deeper understanding of the role of USP7 in cancer using unbiased profiling experiments." (PMID 32210275, 2020). "USP7 is also deregulated in many cancer types, where deviances in USP7 protein levels are correlated with cancer progression." (PMID 32850836, 2020). "Our present findings suggest that targeting factors such as USP44 and USP7 that promote FOXP3 expression at the protein level is a strategy that offers exciting possibilities for the fine‐tuning of immune responses in cancer." (PMID 32644293, 2020). "Based on this concept, we evaluated the expression and inhibitory effects of USP7 in several cancer cells of the prostate, lung, and cervix." (PMID 33207738, 2020). "In this review, we will discuss the many roles USP7 plays in maintaining genome stability and its links with cancer." (PMID 32850836, 2020). "USP7 is a promising target for the development of cancer treatments because of its high expression and the critical functions of its substrates in carcinogenesis of several different carcinomas." (PMID 33207738, 2020). "Overexpression of USP7 is observed in many types of cancers, indicating the therapeutic potential of USP7 as a target." (PMID 32922122, 2020). "USP7 is highly expressed in most cancers, such as breast cancer and colorectal cancer, and plays carcinogenic role by deubiquitinating MDM2 and MDMX." (PMID 33004065, 2020). "In the following section, we will now discuss links between USP7 deregulation and carcinogenesis, as well as strategies for targeting USP7 in anti-cancer therapy." (PMID 32850836, 2020). "Owing to their involvement in cancer development across multiple tumors, USP7 andEZH2 have been considered attractive therapeutic targets and several inhibitorshave been developed for each protein." (PMID 32453339, 2020).